SPDYE9 (speedy/RINGO cell cycle regulator family member E9)
Synonyms: SPDYE9P
Gene: Protein-coding gene on chromosome 7 (73,075,972 to 73,086,038, reverse strand). Ensembl gene ENSG00000262461.
Gene Ontology:
Molecular function: protein kinase binding
Homologues: Orthologues: rat Spdye4 (49% identical), mouse Spdye4a (48% identical), mouse Spdye4b (44% identical). Paralogues in human: SPDYE10 (100% identical), SPDYE11 (100% identical), SPDYE17 (100% identical), SPDYE8 (100% identical), SPDYE13 (99% identical), SPDYE14 (99% identical), SPDYE15 (99% identical), SPDYE12 (99% identical), SPDYE3 (89% identical), SPDYE18 (83% identical), SPDYE16 (83% identical), SPDYE2 (83% identical), and 6 more.